FTL (ferritin light chain)
Diseases named in the same sentence as FTL in open-access papers (continued):
Sharing a sentence is not in itself a finding about the gene and the disease.
glioma (continued). "We used TCGA datasets to analyze the effect of FTL expression on survival time of glioma patients with different treatments." (PMID 32677981, 2020). "To explore the correlation between FTL and glioma aggressiveness, we compared FTL expression in different IDH1/2 status." (PMID 32677981, 2020). "FTL expression positively correlated with HIF1A in glioma tissues and obviously increased in U87 and U251 cells under hypoxia in a time-dependent manner." (PMID 32677981, 2020). "FTL promoted EMT of glioma by regulating AKT/GSK3β/ β-catenin signaling, which subsequently enhanced invasion and chemoresistance of glioma cells." (PMID 32677981, 2020). "The significance of FTL expression was also demonstrated by its correlation with the clinical prognosis of glioma patients." (PMID 32677981, 2020). "FTL expression was enriched in high grade glioma (HGG) and its expression significantly associated with IDH1/2 wildtype and unfavorable prognosis of glioma patients." (PMID 32677981, 2020). "Using IM-12 or CTNNB1 plasmid significant reversed the oncogenic function of FTL in mediating EMT in glioma, which strongly indicated that FTL promoted EMT by regulating AKT/GSK3β/ β-catenin signaling." (PMID 32677981, 2020). "Our results showed that glioma patients with higher FTL expression had worse overall survival than those with lower FTL expression in TCGA, CGGA and Rembrandt datasets." (PMID 32677981, 2020). "Taken together, these results suggested that FTL was a novel biomarker in predicting TMZ response in glioma patients." (PMID 32677981, 2020). "Immunohistochemistry (IHC), western blot and public datasets were used to evaluate FTL level in glioma." (PMID 32677981, 2020). "FTL expression segregated glioma patients who were treated with TMZ or with high MGMT promoter methylation into survival groups in TCGA dataset." (PMID 32677981, 2020). "We found that knocking down FTL in glioma cells dramatically reduced nucleus accumulation of β-catenin and dramatical decrease of activity of β-catenin signaling detected by Luciferase reporter system." (PMID 32677981, 2020). "While overexpression of FTL dramatically increased the survival rate of glioma cells treated with different TMZ concentrations." (PMID 32677981, 2020). "FTL expression was significantly higher in IDH1/2 wildtype gliomas when compared with IDH1/2 mutant gliomas in TCGA and Rembrandt." (PMID 32677981, 2020). "In our study, we found the cytoplasm and nucleus fraction of β-catenin were both decreased after repression of FTL by shRNA in glioma cells." (PMID 32677981, 2020). "Taken together, these results indicated that FTL promoted EMT of glioma cells by regulating AKT/GSK3β/β-catenin signaling." (PMID 32677981, 2020). "Then the results of IHC staining showed that FTL was positively correlated with HIF1A in glioma tissues." (PMID 32677981, 2020). "Altogether, these studies suggest that FTL plays a role in glioma biology, but the precise role of FTL needs to be further investigated." (PMID 28837569, 2017). "Our results showed that FTL expression was higher in GBM patients than in those with low-grade glioma, and that overall survival and disease-free survival was higher in patients with downregulated FTL mRNA." (PMID 26871431, 2016). "By using quantitative real-time RT-PCR, we found that expression of FTL was higher in patients with GBM than in those with low-grade glioma." (PMID 26871431, 2016). "In this study, we assessed FTL expression in glioma samples obtained from human patients, as well as the subcellular distribution of FTL in GBM cells." (PMID 26871431, 2016). "Notably, FTL expression is significantly higher in high-grade gliomas compared to low-grade gliomas." (PMID 41155273, 2025). "In addition, ferritin light chain (FTL) promotes M2 polarization of TAMs by facilitating the ferroptosis pathway through the inhibition of iPLA2β in glioma." (PMID 39614322, 2024).
glioma (continued). "Taken together, these results indicated that FTL could induce M2 macrophage polarization and promote glioma progression by inducing iron overload and ROS generation." (PMID 37441589, 2023). "Previous studies have investigated the role of FTL in promoting glioma progression." (PMID 37441589, 2023). "To explore whether FTL regulates glioma angiogenesis, we analyzed GL261 tumor vasculature by CD31 staining." (PMID 37441589, 2023). "Finally, inhibition of FTL in TAMs attenuated glioma angiogenesis and sensitized glioma to anti-PD1 therapy." (PMID 37441589, 2023). "We concluded that FTL promotes M2 macrophage polarization via promoting the ferroptosis pathway by inhibiting iPLA2β; this polarization of macrophages to the M2 type promotes glioma progression." (PMID 37441589, 2023). "Further, M2 macrophages were positively correlated with FTL in glioma." (PMID 37441589, 2023). "Combining anti-PD1 immunotherapy with FTL inhibition may improve disease response in glioma patients and requires further investigation." (PMID 37441589, 2023). "It is proven that FTL promotes migration, invasion and chemoresistance in glioma." (PMID 36072803, 2022). "Moreover, our study found downregulation FTL decreased the survival rate and increased the apoptosis of glioma cells treated with temozolomide (TMZ)." (PMID 32677981, 2020). "Since FTL mediated TMZ-resistance of glioma cells, we tried to investigate whether FTL could be used as a biomarker of TMZ therapeutic-response." (PMID 32677981, 2020). "We found that hypoxia enhanced the invasion of glioma cells, while inhibition FTL in glioma cells could mostly eliminate hypoxia-promoted invasion." (PMID 32677981, 2020). "Also, knocking down FTL dramatically altered glioma cell to blunt morphology and reduced the migration and invasion of glioma cells, as well as alter expression of snail and E-cadherin." (PMID 32677981, 2020). "While overexpression FTL in glioma cells increased p-AKT (ser473) and p-GSK3β(ser9)." (PMID 32677981, 2020). "Since hypoxia increased FTL level in glioma, we explored whether FTL mediated hypoxia induced EMT of glioma cells." (PMID 32677981, 2020). "Conversely, overexpression FTL significantly enhanced the migration and invasion of glioma cells." (PMID 32677981, 2020). "Then we tried to explore the prognostic value of FTL in gliomas by using public datasets." (PMID 32677981, 2020). "Next, we established stable FTL knockdown glioma cell lines using shRNA." (PMID 32677981, 2020). "The nuclear accumulation of β-catenin correlated with WHO grades and cytoplasmic- nuclear β-catenin was an independent prognostic factors in glioma.FTL positively correlated with β-catenin and the nuclear accumulation of β-catenin was more common in glioma tissues with high FTL expression." (PMID 32677981, 2020). "Ferritin Light Chain (FTL) is one of the iron metabolism regulators and is overexpressed in glioma." (PMID 32677981, 2020). "On the other hand, the results obtained from survival analyses with FTH and FTL and the identified microglial expression suggest that iron-flux in gliomas may be dependent of different cell types and crosstalk between these cell types." (PMID 28837569, 2017). "Moreover, the expression of FTL was analyzed in bulk and at single-cell RNA-seq level, and a comprehensive analysis of the correlation between FTL expression and glioma-infiltrating immune cells was performed, aiming to reveal the potential role of FTL in glioma immunology." (PMID 37441589, 2023). "Moreover, FTL inhibition significantly improved the therapeutic effect of PD1 mab on glioma." (PMID 37441589, 2023). "In addition to TAMs, this study also reported the effect of FTL on T cells in the glioma TME." (PMID 37441589, 2023). "However, the mechanism of FTL in glioma angiogenesis requires further exploration." (PMID 37441589, 2023). "Moreover, FTL can be secreted into blood by glioma cells, detecting the level of FTL in plasma may predict the prognosis of glioma." (PMID 32677981, 2020).
glioma (continued). "Our study provided solid evidence FTL might be a novel regulator of EMT in glioma." (PMID 32677981, 2020). "Moreover, we investigated whether hypoxia induced chemo-resistance was mediated by FTL Inhibition of FTL in glioma cells reduced the clone formation number induced by hypoxia." (PMID 32677981, 2020). "Additionally, it has been shown that FTL knockdown inhibits glioma cell proliferation and increases apoptosis in cells treated with TMZ, suggesting that FTL may contribute to TMZ resistance in glioma, and its regulation by HIF-1α represents a potential therapeutic target." (PMID 41155273, 2025). "HE and IHC staining showed that glioma cells from C57BL/6N mice implanted with GL261 and FTL-overexpressing macrophages had a higher proliferative capacity." (PMID 37441589, 2023). "FTL expression level was higher in GBM than that in other glioma subtypes and FTL was positively correlated with glioma grade." (PMID 37441589, 2023). "Through bioinformatics analysis and in-house cohort validation, we have identified FTL as a novel biomarker of prognosis, as well as response to TMZ in glioma." (PMID 32677981, 2020). "Functionally, we showed that FTL induced the EMT and promoted migration, invasion and chemo-resistance of glioma both in vitro and in vivo." (PMID 32677981, 2020). "Taken together, we demonstrated that hypoxia induced FTL promoted EMT by regulating AKT/GSK3β/β-catenin signaling, which subsequently enhanced invasion and chemoresistance of glioma cells." (PMID 32677981, 2020). "In order to explore the role of FTL in inducing EMT process, we analyzed glioma subtype-specific FTL expression in TCGA and Rembrandt datasets." (PMID 32677981, 2020). "In The Cancer Genome Atlas (TCGA) dataset, a negative correlation was found between overall survival and high mRNA levels of TfR1, FTL, and FTH in gliomas." (PMID 28837569, 2017). "In addition, single-cell analyses of glioma samples based on GSE135045 and GSE202371 databases were performed, and FTL was enriched in TAMs." (PMID 37441589, 2023). "In present study, we reported FTL could enhance immunosuppressive TME by promoting M2 macrophage polarization, thereby facilitating the malignant progression of glioma cells." (PMID 37441589, 2023). "Furthermore, we found that knockdown FTL dramatically repressed EMT and reduced migration and invasion of glioma by regulating AKT/GSK3β/ β-catenin signaling both in vitro and in vivo." (PMID 32677981, 2020). "Our previous study revealed that FTL was elevated in glioma tissues when compared with non-tumor brain tissues by RT-PCR in a small glioma cohort." (PMID 32677981, 2020). "Together, FTL could enhanced TMZ resistance and decreased the cytotoxic effect of TMZ therapy on glioma cells." (PMID 32677981, 2020). "Overall, our study revealed that HIF1A directly bond with HRE-3 in the region of FTL promoter to enhance its expression and FTL might act as a crucial gene that regulated EMT process of glioma." (PMID 32677981, 2020). "While the effect of hypoxic environment on FTL expression and its regulation in process of glioma malignancy have not been well investigated so far." (PMID 32677981, 2020). "Targeting FTL in glioma cells could dramatically inhibit EMT induced by hypoxia, which indicated that FTL could be a potential target for therapy." (PMID 32677981, 2020). "Upregulation of FTL expression in glioma had been found in several studies, but the relationship of FTL expression and prognosis of glioma has not been well documented." (PMID 32677981, 2020). "In addition, we wanted to investigate the prognostic potential of TfR1, FTL, and FTH in individual glioma grades, since this aspect is of high clinical interest." (PMID 28837569, 2017). "Considering the correlation between FTL expression and IDH1/2 or subtypes, use of combination molecular analysis containing FTL might provide a more effective method for predicting prognosis of glioma." (PMID 32677981, 2020).
glioma (continued). "To further determine the mechanism by which hypoxia induced FTL expression, we treated U87 and U251 cells with cobalt chloride (CoCl2,400 mM) for 24 h.The results showed that inhibition HIF1A degradation dramatically promoted the expression of FTL in glioma cells." (PMID 32677981, 2020).
iron deficiency (17 papers, 2013 to 2026). "Iron supplementation in both iron-deficient anemia mice and their offspring significantly upregulated FTL levels with improved physical growth compared to untreated mice." (PMID 35745181, 2022). "The presented results indicate that in the CNS of PrPC-null mice, the expression of copper- (Cp, Ctr1, Ccs1) and iron-binding proteins (Tf, TfR1, FtH, FtL, Fpn1) is regulated in line with a copper and iron deficiency status." (PMID 27729845, 2016). "Our results showed that Sev decreased the FtL expression, indicating that Sev caused the iron deficiency in oligodendrocytes which might be one of the important mechanisms of inhibiting myelination growth and development." (PMID 38334030, 2024). "FTL, as a core component of the ferritin complex, exerts a dual role in iron homeostasis: under conditions of high intracellular iron, it sequesters iron within ferritin to limit oxidative damage, whereas under iron deficiency, it can facilitate iron release to support cellular metabolism." (PMID 41560817, 2026). "Similar to DFO responses in HIB1B and C3H/10T1/2 cells, DFO treatment resulted in depletion of iron-storage protein FTL, stabilization of IRP2, and a robust increase of TfR1 expression in adipocytes as a collective sign of iron deficiency." (PMID 33631196, 2021). "We demonstrate that these cells with loss of miR-485-3p function are in a greater state of iron deficiency, as evidenced by increased levels of IRP2 protein, increased TFRC mRNA expression, and decreased ferritin light chain (FTL) mRNA expression." (PMID 23593016, 2013). "Cells with lost miR-17-5p function showed a greater degree of iron deficiency, as evidenced by increased protein levels of IRP2, increased transferrin receptor (TFRC) mRNA expression, and decreased ferritin light chain (FTL) and ferritin heavy chain 1 (FTH1) mRNA expression." (PMID 31423010, 2019). "We speculate that FTL may be more important for suppressing lipid peroxidation, while FTH1 primarily prevents anemia and preserves iron delivery to myelinating oligodendrocytes in the setting of functional iron deficiency." (PMID 39334701, 2024). "In our proteomic study, the expression levels of FTL and FTH1 were both decreased in the high myopia group, while the TF abundance was increased in the high myopia group compared to the low myopia group, indicating the potential impact of iron deficiency on the progression of myopia." (PMID 34660571, 2021).
hyperferritinemia (12 papers, 2011 to 2025). "Three mutations in the N-terminal region of FTL are known to cause amino acid substitutions at positions 26, 27, and 30 in the heterozygous state in the A helix of L-ferritin, resulting in benign hyperferritinemia." (PMID 36768886, 2023). "These include hereditary hyperferritinemia cataract syndrome (HHCS) due to mutations in the IRE region of FTL, so-called benign hyperferritinemia due to mutations in the first exon of FTL, and ferroportin disease due to loss-of-function mutations of SLC40A1." (PMID 36768886, 2023). "(B) Luciferase activity of HepG2 cells transfected with mRNAs encoding the WT FTL 5ʹ-UTR or various hyperferritinemia mutations (G51C, G52C, or Loop mutant (A15G/G16C)), normalized to WT FTL reporter luciferase luminescence." (PMID 31414986, 2019). "There are three known mutations in the N-terminal region of the FTL gene that cause benign hyperferritinemia." (PMID 30678075, 2019). "Here, we show that human eukaryotic translation initiation factor 3 (eIF3) acts as a distinct repressor of FTL mRNA translation, and eIF3-mediated FTL repression is disrupted by a subset of SNPs in FTL that cause hyperferritinemia." (PMID 31414986, 2019). "In the family with the “ii” blood group we found a novel GCNT2 mutation c.G935A (p.G312D) in the cataract patients, while in the family with hyperferritinemia cataract syndrome we identified a G→C heterozygous mutation at position +32 of FTL." (PMID 21541272, 2011). "Single-nucleotide polymorphisms (SNPs) in the 5ʹ untranslated region (5ʹ-UTR) of the ferritin light chain (FTL) gene that cause hyperferritinemia are reported to disrupt translation repression by altering iron regulatory protein (IRP) interactions with the FTL mRNA 5ʹ-UTR." (PMID 31414986, 2019). "We found that disruption of eIF3-mediated regulation of FTL translation could serve as the dominant cause of certain cases of hyperferritinemia." (PMID 31414986, 2019). "In benign hyperferritinemia, missense variations in exon 1 of FTL increase the hydrophobicity of the ferritin N-terminal site." (PMID 30678075, 2019). "Inherited isolated hyperferritinemia includes several rare or ultra-rare disorders caused by mutations in genes directly involved in iron metabolism (FTL, CP, SLC40A1) or not, such as GBA1." (PMID 36768886, 2023). "Variants in the FTL gene causing an isolated hyperferritinemia without any symptoms are also reported and are referred to as benign hyperferritinemia." (PMID 34067164, 2021). "Three heterozygous mutations in FTL exon 1 have been associated with hyperferritinemia without iron overload where cataracts were absent; this condition has also been named benign hyperferritinemia." (PMID 30678075, 2019). "These experiments reveal that eIF3 acts as a repressor of FTL translation, and disruption of eIF3 interactions with FTL mRNA due to specific SNPs in the FTL 5ʹ-UTR likely contributes to a subset of hyperferritinemia cases." (PMID 31414986, 2019). "Characterization of hereditary hyperferritinemia-cataract syndrome reveals a predominant increase in FtL with normal FtH levels and no significant signals of proinflammatory pathway activation at quiescence despite the presence of hyperferritinemia." (PMID 38779751, 2024). "This group includes disorders with or without iron overload caused by defects in genes involved in iron metabolism (FTL, SLC40A1, CP), as well as non-iron-related genetic disorders often associated with hyperferritinemia with normal TSAT." (PMID 36768886, 2023). "Hereditary hyperferritinemia-cataract syndrome (HHCS) and benign hyperferritinemia, respectively, due to mutations in the iron responsive element (IRE) of the L-ferritin gene (FTL) and in the first exon of FTL, have normal TSAT and no iron overload." (PMID 34828384, 2021).
hyperferritinemia (continued). "Benign hyperferritinemia or genetic hyperferritinemia without iron overload (OMIM#600886, ORPHA:254704) is another FTL mutated disorder where patients have high (greater than 90%) glycosylated serum ferritin levels." (PMID 30678075, 2019). "Rare genetic causes of hyperferritinemia without an associated iron overload include hereditary hyperferritinemia cataract syndrome (HHCS), caused by variants in the ferritin light-chain gene (FTL gene)." (PMID 34067164, 2021).